SOX2 (SRY-box transcription factor 2)
Diseases named in the same sentence as SOX2 in open-access papers (continued):
Sharing a sentence is not in itself a finding about the gene and the disease.
pituitary tumor (15 papers, 2011 to 2025). A benign or malignant neoplasm affecting the pituitary gland. "The occurrence of pituitary tumors was markedly reduced in p27−/− mice when one SOX2 allele was inactivated, suggesting a role for SOX2 as oncogene." (PMID 29255445, 2017). "Loss of this regulation leads to unscheduled expression of Sox2 in differentiated cells with the drastic phenotypic consequences that characterize p27-null mice: gigantism, pituitary tumor development, and retinal defects." (PMID 25576924, 2015). "This is the first indication that SOX2 haploinsufficiency is implicated in the generation of pituitary tumors with distinct clinical characteristics, possibly mediated via its effects on the Wnt signaling pathway." (PMID 21919124, 2011). "However, in addition to hypothalamic deficits, it is notable that SOX2 variants in humans have been previously linked to several pituitary defects: anterior pituitary hypoplasia and slowly progressing pituitary tumors." (PMID 36602867, 2023). "Another study utilised immunofluorescence in human pituitary tumours to demonstrate expression of stem cell markers, SOX2 and SOX9, in a variety of clinical tumour types." (PMID 38483762, 2024). "To determine if pituitary tumors of fetal alcohol-exposed rats contains PSCs, we measured stem cell marker proteins SOX2, CD133 and OCT4 by immunocytochemistry and their precursor genes by q-PCR in the tumor tissues." (PMID 29769550, 2018). "In this regard and in line with our above observations, the incidence of pituitary tumors was significantly reduced in Sox2-het/p27-null mice compared to p27 null littermates." (PMID 23217425, 2012). "It is intriguing that only the two patients described in this study, out of many known patients with SOX2 haploinsufficiency, developed pituitary tumors." (PMID 21919124, 2011). "In this study, we found higher protein and/or mRNA levels of DPPA4‐associated stem cell factors (SOX‐2, OCT‐4, KLF‐4, SNAIL‐1, and Nestin) in PAE male pituitaries, suggesting that PAE similarly enhances estrogen‐induced pituitary tumor cell stemness in both sexes." (PMID 41017273, 2025). "Further research on the regulation of Sox2 expression might lead to better treatments for male infertility and other transcription factors including ophthalmic defects and pituitary tumors." (PMID 37663428, 2023). "Postnatal deletion of LATS kinases and subsequent upregulation of YAP/TAZ leads to uncontrolled clonal expansion of the SOX2+ PSCs and disruption of their differentiation, causing the formation of non-secreting, aggressive pituitary tumours." (PMID 30912742, 2019). "The pituitary tumor SP was found enriched in cells with pronounced expression of tumor stemness markers (such as SOX2 and the chemokine C-X-C motif receptor 4, CXCR4) and of stem cell-associated signaling pathways [such as epithelial–mesenchymal transition, (EMT)]." (PMID 29255445, 2017). "The functional consequences of the defective repression of Sox2 are manifested in the cellular reprogramming of Rb deficient cells to iPSCs in the absence of exogenous Sox2, and in vivo in Rb loss-driven pituitary tumor development." (PMID 25576924, 2015). "Finally, Sox2 haploinsufficiency genetically rescues some of the phenotypes characteristic of p27 null mice, including gigantism, pituitary hyperplasia, pituitary tumors, and retinal defects." (PMID 23217425, 2012). "Here, we report two unrelated patients with SOX2 haploinsufficiency (a heterozygous gene deletion and a novel c.143TC>AA/p.F48X mutation) who developed nonprogressive pituitary tumors of early onset, suggesting a congenital etiology." (PMID 21919124, 2011). "Furthermore derepression of Sox2 is also observed in pRb+/− pituitary tumors." (PMID 33574062, 2021). "Compared to pituitary tumours meeting clear lineage criteria, we found WDLD tumours more frequently expressed stem cell markers SOX2 and CD133 on IHC, the majority of which exhibited strong SOX2 intensity." (PMID 38483762, 2024).
pituitary tumor (continued). "However, the fact that we found Sox2+ cells in more than one-third of the tumours surrounding brain tissue may point to the recently suggested non-cell-autonomous role of Sox2+ stem/progenitor cells as observed in murine pituitary tumour formation." (PMID 29158570, 2017). "Analysis of p27−/−; Srr2del/del animals shows that the repressive action of P27 is mediated by Srr2 and in absence of p27, Srr2 activators drive Sox2 expression; this then leads to pituitary tumors and retina defects (see model)." (PMID 33574062, 2021). "Interestingly, the characteristic gigantism of p27 null mice was normalized by deletion of one Sox2 allele, as was also the case for the pituitary mass in young 3- to 6-month-old mice (at this age, p27 null mice present pituitary hyperplasia, but do not have pituitary tumors yet)." (PMID 23217425, 2012). "Therefore, our results showing increased SOX2, OCT4, and other stem cell markers in PAE male pituitary tumors suggest that overexpression of stem cell markers, which may contribute to their aggressiveness." (PMID 41017273, 2025). "Similarly, targeted expression of oncogenic β-catenin in SOX2+ cells is reported to give rise to other tumor types in a non-cell-autonomous manner (e.g., pituitary tumors)." (PMID 31041783, 2019). "Furthermore, it was demonstrated that SOX2 and SOX9 expressing progenitor cells can self-renew and give rise to endocrine cells in vivo, suggesting that they are tissue stem cells, playing a role in the physiological maintenance of the pituitary gland as well as in the induction of pituitary tumors." (PMID 35805171, 2022). "Genetic lineage tracing identified SOX2+ cells as the cell of origin of the tumours; this observation could have ramifications regarding involvement of the LATS/YAP/TAZ pathway in the establishment or progression of human pituitary tumours composed of uncommitted cells." (PMID 30912742, 2019).
viral infection (15 papers, 2015 to 2025). "Switches of SOX17 and SOX2 expression in the development of squamous metaplasia and squamous intraepithelial lesions of the uterine cervix are associated with viral infection." (PMID 32644288, 2020). "Alternatively, the proliferative capacity and thus the susceptibility of the Sox2+ population to viral infection could differ between developmental models and the adult DG, where in adult neurogenesis Sox2+ cells are largely quiescent and perhaps less sensitive to virus-induced cell death." (PMID 34259630, 2021). "Different factors such as morphogen gradients or viral infections can influence the morphology of SOX2+ structures in brain organoids." (PMID 39034883, 2024). "HERV-K is transiently reactivated in early human development to protect cells from the threat of exogenous viral infection; however, HERV-K retrotransposition entails a risk of genomic impairment in SOX2-expressing cells, such as iPSCs." (PMID 35420440, 2022). "Most importantly, viral infection confirmed by ZIKVBR NS2B immunolabeling and positive TUNEL staining was found in tumor cells SOX2−, suggesting virus infection preference when compared with the stem-like normal cell, SOX2+." (PMID 34696533, 2021). "We detected viral infection in both SOX2+ airway and SOX9+ alveolar cells." (PMID 37084725, 2023). "Notably, the Sox2 staining indicated that the viral infection efficiency was about 43.7%." (PMID 34222247, 2021). "To answer the question whether or not HPV infection results in a switch of SOX expression, we studied the association between the topographic localization of SOX17 and SOX2 expressing epithelia and the viral infection as detected by p16 and ISH, using 23 cases of SIL that could be studied in detail." (PMID 32644288, 2020). "To establish the in vivo function of airway epithelial LMP7 in lung viral infection, we generated tamoxifen-inducible LMP7 CKO mice that have the Sox2 open reading frame." (PMID 36008456, 2022). "IHC analysis of fetal CNS tissues from some of these fetuses detected ZIKV NS5 staining in Sox2+ cells in the neocortical ventricular zone, suggesting that virus infection of the fetus occurred in the absence of placental barrier breakdown." (PMID 28775298, 2017). "On day 14 after viral infection, RT-qPCR analysis showed that the expression levels of endogenous NANOG, OCT4, and SOX2 were increased in H9-OCT4pGFPdF populations co-expressing OSKM and circBIRC6 (OSKMB) or circCORO1C (OSKMC) compared with H9-OCT4pGFPdFs expressing only OSKM." (PMID 29074849, 2017). "We found that molecules like SOX2, FGFR3, and CDKN1B could be more affected by different viruses than other molecules shaping the auditory system, suggesting that cochlear development and production of hair and supporting cells might be disrupted by certain viral infections during embryogenesis." (PMID 33419104, 2021).
ZIKV infection (15 papers, 2016 to 2024). "The presence of SOX2 was further associated with an enhanced oncolytic effect promoting viral entry and ZIKV infection, in association with ITGA5." (PMID 37686355, 2023). "In contrast, neuron-specific Class III β-tubulin (TuJ1)-positive neurons in the astrocyte cultures and SOX2-positive neural progenitor cells derived from the fetal brains were less susceptible to ZIKV infection compared with astrocytes." (PMID 29707233, 2018). "Therefore, SOX2 can be used as a prediction marker for successful virotherapy as the expression level of SOX2 in GSCs can predict their susceptibility to ZIKV infection and subsequent virotherapy response." (PMID 40342640, 2024). "Thus, because Sox2+ cells are on intense proliferation, it is likely that ZIKV infection causes the reduction of cell proliferation and increased apoptosis in part by the induction of mitotic dysfunctions described herein." (PMID 28008958, 2016). "This positive correlation between the levels of SOX2 expression and ZIKV infection suggests the potential utility of SOX2 as a therapeutic marker for predicting successful treatment outcomes." (PMID 40342640, 2024). "In order to correlate this impairment of NPCs with ZIKV infection, 4 dpf brain sections were co-stained with antibodies directed against Sox2 and ZIKV E protein." (PMID 39621753, 2024). "Instead we found that SOX2+ progenitors in GBM were refractory to ZIKV infection relative to HDB SOX2+ progenitors, and that this property derived from non-contact mediated effects of myeloid cells." (PMID 36174572, 2022). "Consistently, the decrease in SOX2-positive cells after ZIKV infection was relieved by ouabain treatment, demonstrating that developmental defects were substantially reduced by ouabain treatment of ZIKV-infected pregnant mice." (PMID 32669655, 2020). "To further examine the protective action of BA in Sox2+-NPCs population, we generated cerebral organoids from iPSCs and performed ZIKV infection." (PMID 33251156, 2020). "Studies suggested that the SOX2+ neural progenitor cells (NPCs) are the directed target of ZIKV infection in human brain organoids." (PMID 31086212, 2019). "The ZIKV infection of these astrocytes appear to be quite specific since both TuJ1-positive neurons in the astrocyte cultures and SOX2-positive NPCs derived from the fetal brains appear to be less susceptible compared with astrocytes." (PMID 29707233, 2018). "Although our study focused on the aspect of the role of SOX2 expression levels and ZIKV infection, the limitations may include the exclusion of immune responses in our modeling approaches." (PMID 40342640, 2024). "We compared productive ZIKV infection in HDB and GBM primary tissue explants that both contain SOX2+ neural progenitors." (PMID 36174572, 2022). "In particular, it was demonstrated that SOX2 promotes ITGA5 and enhances ZIKV infection." (PMID 37686355, 2023). "Nevertheless, human embryonic stem cells and iPSCs are not highly permissive to ZIKV infection, despite high SOX2 expression and proliferative capacity, suggesting additional factors are involved." (PMID 36174572, 2022). "Co-staining demonstrated ZIKV infection was in early neuroprogenitor Sox2+ cells and not mature NeuN+ neurons." (PMID 28775298, 2017). "Our results indicated that ZIKV infection did not affect SOX1 or SOX2 patterns." (PMID 35714598, 2022).
cervical squamous cell carcinoma (14 papers, 2014 to 2025). A squamous cell carcinoma arising from the cervical epithelium. "A few studies have reported that SOX2 is overexpressed in cervical squamous cell carcinoma (SCC), and plays an important role in the progression from squamous dysplasia to SCC." (PMID 33789601, 2021). "The StarBase database was used to analyze the coexpression of TAB2 and classical stemness molecules (BMI1 and SOX2) in 306 cervical squamous cell carcinoma samples." (PMID 34306095, 2021). "In cervical squamous cell carcinoma, high expression of SOX2 along with high expression of OCT4 indicated resistance to radiotherapy, and both factors were important predictors of poor patient survival." (PMID 32093282, 2020). "The aim of this study was to elucidate the value of putative cancer stem cell markers Musashi-1, ALDH1, Sox2, and CD49f in predicting the prognosis in cervical squamous cell carcinoma (CSCC)." (PMID 26499463, 2015). "SOX2 is an important transcription factor for the acquisition and maintenance of stem cell properties and is a well-recognized marker of CSCs including CSCs of cervical squamous cell carcinoma." (PMID 35860042, 2022). "Furthermore, SOX2 was reported to be regulator of HPV16 at the transcriptional level in cervical squamous cell carcinoma." (PMID 33789601, 2021). "SOX2 expression in high-grade cervical intraepithelial neoplasia (CIN3) and cervical squamous cell carcinomas has been reported to be higher than in the normal cervical epithelium." (PMID 35945296, 2022). "SOX2 expression in high-grade cervical intraepithelial neoplasia (CIN3) and cervical squamous cell carcinoma is increased compared to that in the normal cervical epithelium." (PMID 35945296, 2022). "High expression of SOX2 and OCT4 indicates radiation resistance in cervical squamous-cell carcinoma." (PMID 31114449, 2019). "Immunohistochemistry showed that SOX2 and TP63 proteins clearly delineated tumour cells in invasive squamous cervical cancer." (PMID 25531390, 2014). "SOX2, HCG and TP63 mRNAs were also shown to be upregulated in cervical samples with HR-HPV+ve high grade dyskaryosis and SOX2 and TP63 immunohistochemistry identified cancerous cells, in HR-HPV+ve biopsies, from women with cervical squamous cell carcinoma." (PMID 25531390, 2014). "In TCGA-cervical squamous cell carcinoma (CESC) cohort, CBX2 expression was positively correlated with the expression of the cancer stem cell markers SOX2 and ALDH1A1." (PMID 39793896, 2025). "SOX2 and PRKCI display lower levels of mRNA over-expression in 3q26-amplified squamous cervical cancers, while MECOM and TERC show no over-expression." (PMID 34436017, 2021). "NANOG and SOX2 expression was evaluated immunohistochemically on 40 patients: in 10 cases each of low-grade SIL (LSIL), high-grade SIL/CIN, grade 2 (HSIL/CIN 2), HSIL/CIN, grade 3 (HSIL/CIN 3), cervical squamous cell carcinoma (CSCC) and their adjacent non-dysplastic squamous epithelium." (PMID 40272007, 2025).
serous ovarian cancer (14 papers, 2015 to 2024). "In human serous ovarian cancer cells, SOX2 overexpression increased CSC marker expression, sphere formation, and in vivo tumorigenic activity, with little effect on cell proliferation." (PMID 27489349, 2016). "ELF3 knockdown reduced SOX2 and POU5F1/OCT4 expression, whereas overexpression of ELF3 increased SOX2 and POU5F1 expression in high-grade serous ovarian cancer cells." (PMID 36289818, 2022). "An high-grade serous ovarian cancer (HGSOC) cell line, OVCAR-3 was reprogrammed by transducing Yamanaka four factors OCT4, SOX2, KLF4 and MYC (OSKM) to establish an iOCIC model, iOVCAR-3-OSKM." (PMID 36085021, 2022). "For instance, the rates of SOX2 and ST6GAL1 CNG within the ovarian serous carcinoma cohort (*) are 27 and 24%, respectively." (PMID 31610800, 2019). "Similar morphologic changes of epithelial cells in the ovarian surface epithelium of women with the ovarian serous carcinoma were found after staining ovarian sections for pluripotency-related markers SSEA-4 and SOX2, using immunofluorescence." (PMID 28231820, 2017). "Similar populations of SOX2 and SSEA-4-positive cells were found in ovarian sections of women with high-grade serous ovarian carcinoma and their expression nicely matched with NANOG expression." (PMID 26940129, 2016). "In 27 women with borderline ovarian cancer and 20 women with high-grade serous ovarian carcinoma the ovarian tissue sections were stained, per standard practice, with eosin and hematoxylin staining and on NANOG, SSEA-4 and SOX2 markers, related to pluripotency, using immunohistochemistry." (PMID 26940129, 2016).